ZDHHC9 (zDHHC palmitoyltransferase 9)
Description:
Palmitoyltransferase that catalyzes the addition of palmitate onto various protein substrates, such as ADRB2, GSDMD, HRAS, NRAS and CGAS. The ZDHHC9-GOLGA7 complex is a palmitoyltransferase specific for HRAS and NRAS. May have a palmitoyltransferase activity toward the beta-2 adrenergic receptor/ADRB2 and therefore regulate G protein-coupled receptor signaling. Acts as a regulator of innate immunity by catalyzing palmitoylation of CGAS, thereby promoting CGAS homodimerization and cyclic GMP-AMP synthase activity. Activates pyroptosis by catalyzing palmitoylation of gasdermin-D (GSDMD), thereby promoting membrane translocation and pore formation of GSDMD. (Microbial infection) Through a sequential action with ZDHHC20, rapidly and efficiently palmitoylates SARS coronavirus-2/SARS-CoV-2 spike protein following its synthesis in the endoplasmic reticulum (ER). In the infected cell, promotes spike biogenesis by protecting it from premature ER degradation, increases half-life and controls the lipid organization of its immediate membrane environment. Once the virus has formed, spike palmitoylation controls fusion with the target cell.
Synonyms: DHHC9; CXorf11; ZDHHC10; ZNF379; ZNF380; CGI-89; CGI89; MMSA1; MRXSR; MRXSZ
Tractability: Small molecule: a structure with a bound ligand is known. Antibody: UniProt predicts a signal peptide or a membrane-spanning region. PROTAC: ubiquitination databases record sites on it.
Target class: Enzyme; Transferase
Gene: Protein-coding gene on chromosome X (129,803,288 to 129,844,215, reverse strand). Ensembl gene ENSG00000188706.
Subcellular location: Endoplasmic reticulum membrane; Golgi apparatus membrane
Subcellular location (Human Protein Atlas): Endoplasmic reticulum; Golgi apparatus; Cytosol
Pathways (Reactome):
Disease: Maturation of spike protein
Signal Transduction: RAS processing
Gene Ontology:
Molecular function: palmitoyltransferase activity; protein binding; protein-cysteine S-palmitoyltransferase activity; Ras palmitoyltransferase activity
Biological process: host-mediated activation of viral process; peptidyl-L-cysteine S-palmitoylation; positive regulation of cGAS/STING signaling pathway; positive regulation of pyroptotic inflammatory response; post-translational protein modification; MAPK cascade; protein targeting to membrane
Cellular component: endoplasmic reticulum; endoplasmic reticulum membrane; Golgi apparatus; Golgi membrane; palmitoyltransferase complex; endoplasmic reticulum-Golgi intermediate compartment membrane
Gene-disease validity (ClinGen):
ClinGen rates the evidence that ZDHHC9 causes each of these diseases.
syndromic X-linked intellectual disability Raymond type (X-linked): Definitive. A syndromic X-linked intellectual disability characterized by intellectual disability and marfanoid habitus that has material basis in mutation in the ZDHHC9 gene on chromosome Xq26.1.
Homologues: Orthologues: chimpanzee ZDHHC9 (100% identical), rabbit ZDHHC9 (99% identical), guinea pig ZDHHC9 (99% identical), rat Zdhhc9 (99% identical), mouse Zdhhc9 (98% identical), dog ZDHHC9 (98% identical), pig ZDHHC9 (98% identical), macaque ZDHHC9 (88% identical), tropical clawed frog zdhhc9 (80% identical), zebrafish zdhhc9 (74% identical), Caenorhabditis elegans dhhc-2 (37% identical), Drosophila melanogaster CG1407 (20% identical), and 7 more. Paralogues in human: ZDHHC14 (58% identical), ZDHHC18 (51% identical), ZDHHC2 (20% identical), ZDHHC1 (19% identical), ZDHHC20 (19% identical), ZDHHC3 (19% identical), ZDHHC15 (17% identical), ZDHHC7 (17% identical), ZDHHC4 (16% identical), ZDHHC19 (16% identical), ZDHHC12 (15% identical), ZDHHC22 (15% identical), and 5 more.
Diseases named in the same sentence as ZDHHC9 in open-access papers:
ZDHHC9 is named in the same sentence as 64 diseases in open-access papers, as found by Europe PMC text mining. Sharing a sentence is not in itself a finding about the gene and the disease. The quoted sentences say what the papers report.
breast carcinoma (15 papers, 2016 to 2026). "Disrupting PD-L1 palmitoylation through specific point mutations at the Cys272 site or inhibiting ZDHHC9 expression makes breast cancer cells sensitive to T-cell killing, thereby inhibiting tumor growth." (PMID 38762484, 2024). "Disruption of PD-L1 palmitoylation by preventing ZDHHC9 expression makes breast cancer cells more susceptible to T-cell-initiated death, which inhibits tumor development." (PMID 38177255, 2024). "In particular, the mechanisms underlying the effects of ZDHHC9 on immune cell infiltration in breast cancer warrant further investigation and validation." (PMID 37875591, 2023). "Inhibiting the ZDHHC9 expression made breast cancer cells susceptible to T cell killing and inhibited tumor growth." (PMID 34956313, 2021). "Disruption of PD-L1 palmitoylation by site-specific mutation (C272A) of PD-L1 or knock-down of ZDHHC9 reduces PD-L1 cell surface distribution, sensitizes breast cancer cells to T cell killing, and inhibits tumor growth in vivo." (PMID 34829931, 2021). "In breast cancer, ZDHHC9 enhances PD-L1 stability through palmitoylation, and ZDHHC9 deficiency in lung cancer prevents PD-L1 degradation, enhancing the effectiveness of anti-PD-L1 immunotherapy." (PMID 38654302, 2024). "Mutation of Cys272 to Ala dramatically abolishes mPD-L1 palmitoylation, or inhibiting the expression of zDHHC9 sensitizes breast cancer cells to T-cell killing, thereby repressing tumor growth." (PMID 38415253, 2024). "In breast cancer, PD-L1 has been found to be palmitoylated by zDHHC9 at the C272 site, enhancing its stability." (PMID 38415253, 2024). "Analysis of data from several public datasets revealed that patients with high ZDHHC9 expression had an increased proportion of Ki-67 + breast cancer cells and tended to be basal-like breast cancer." (PMID 37875591, 2023). "Different from the studies conducted on breast cancer, colorectal cancer, and lung adenocarcinoma, this study found that, in the pancreatic tumor xenograft model, tumors with ZDHHC9 knockdown led to a change in PD-L1 level on the surrounding immune cells." (PMID 37759431, 2023). "In public datasets, patients with high ZDHHC9 expression had an increased proportion of Ki-67 + breast cancer cells and tended to have basal-like breast cancer." (PMID 37875591, 2023). "In the 233 breast cancer cases in TCGA cohort, ZDHHC9 expression significantly predicted a poor prognosis (HR = 1.94, p = 0.046) and was significantly negatively correlated with the infiltration of CD8 + T cells and NK cells (p < 0.001)." (PMID 37875591, 2023). "ZDHHC9-mediated palmitoylation maintains the stability and cell surface distribution of PD-L1, leading to immune escape of breast cancer cells, whereas overexpression of ZDHHC9 greatly inhibits the proliferation of colorectal cancer cells." (PMID 37875591, 2023). "Inhibition of zDHHC9-mediated palmitoylation of PD-L1 makes breast cancer cells more sensitive to T cell immune killing." (PMID 35637973, 2022). "Two palmitoyltransferases, ZDHHC9 in breast cancer and ZDHHC3 (DHHC3) in colorectal cancer, attach palmitate to the C272 site of PD-L1." (PMID 34829931, 2021). "ZDHHC9, which has been associated with colorectal cancer and glioblastoma, was upregulated in breast cancer tissues, especially TNBC tissues, compared with other molecular subtypes of breast cancer." (PMID 37875591, 2023). "In addition, ZDHHC9-mediated palmitoylation maintains the stability and cell surface distribution of PD-L1 protein, enabling immune escape of breast cancer cells." (PMID 37875591, 2023). "However, the expression of ZDHHC9 in breast cancer subtypes, including TNBC, and its effects on immune cell infiltration within the tumor have not been reported." (PMID 37875591, 2023).
breast carcinoma (continued). "In addition, patients with high ZDHHC9 expression had an increased proportion of Ki-67 + breast cancer cells and tended to have basal-like breast cancer in several datasets, including GSE16228, GSE20711, GSE21653 and GSE48390 datasets." (PMID 37875591, 2023). "PD-L1 was found to be palmitoylated at C272 by ZDHHC9 in breast cancer to enhance its stability." (PMID 36577755, 2022). "On the other hand, ZDHHC9, a known gene closely related with RAS protein has been found to be over expressed in kinds of human malignancies such as breast cancer and colon cancer." (PMID 41535418, 2026). "In our study, we found that RAS was over activated by MMSA-1, both in mRNA level and protein levels, just like its overactivation mechanism by ZDHHC9 in breast cancer." (PMID 41535418, 2026). "In accordance with the gene expression levels, the protein levels of ZDHHC9, PCMT1, TMEM70 were significantly higher in breast cancer, and the protein levels of IRF2, KCNJ11 were higher in normal tissues." (PMID 34956313, 2021). "In addition, ROC analysis revealed that the four genes had higher AUC values for predicting the diagnosis of breast cancer (TBC1D24, AUC = 0.798; TRIM67, AUC = 0.711; ZDHHC9, AUC = 0.810; QRSL1, AUC = 0.801)." (PMID 37875591, 2023). "Our results indicated that high expression of ZDHHC9 had a negative effect on OS, relapse-free survival (RFS), disease-specific survival (DSS) and progression-free survival (PFS) in breast cancer patients in a multi-centre retrospective cohort." (PMID 37875591, 2023). "Of note, unlike ZDHHC9-mediated PD-L1 palmitoylation in breast cancer cells, palmitoylation of PD-L1 in colorectal cancer cells is mediated by ZDHHC3 but not ZDHHC9, indicating that PD-L1 utilizes multiple ZDHHCs to ensure its palmitoylation in different contexts." (PMID 37759431, 2023).
glioblastoma (14 papers, 2021 to 2025). The most malignant astrocytic tumor (WHO grade IV). "ZDHHC9-mediated GLUT1 S-palmitoylation, which maintains the plasma membrane localization of GLUT1, is critical for glucose supply during glioblastoma multiforme (GBM) tumorigenesis." (PMID 38821916, 2024). "Studies have shown that zDHHC9 mediates the S-palmitoylation of GLUT1 at C207, promoting its plasma membrane localization and resulting in heightened glycolysis in glioblastoma." (PMID 38415253, 2024). "For example, ZDHHC9 maintains the palmitoylation and plasma membrane expression of GLUT1, which is crucial for glucose transport in glioblastoma cells." (PMID 39563863, 2024). "For instance, recent study demonstrated that ZDHHC9-mediated palmitoylation of Glucose transporter 1 (GLUT1) plays a decisive role in the localization of GLUT1, and palmitoylated GLUT1 can promote glioblastoma glycolysis and tumorigenesis." (PMID 37161425, 2023). "Researchers found that ZDHHC9 mediates the palmitoylation of GLUT1 at C207 and promotes its PM localization process, leading to a high level of glycolysis and glioblastoma (GBM) tumorigenesis." (PMID 36577755, 2022). "ZDHHC9-mediated GLUT1 S-palmitoylation promotes glycolysis and tumorigenesis in glioblastoma." (PMID 37875591, 2023). "ZDHHC9 facilitates palmitoylation of Glucose transporter (GLUT1) at Cys207 and thus increases its plasma membrane localization, which is critical for glucose supply during glioblastoma (GBM) tumorigenesis." (PMID 35637973, 2022).
Intellectual disability (10 papers, 2016 to 2025). "A relevant gene for studying the emergence of intellectual disabilities is ZDHHC9, which encodes a palmitoylation enzyme (ZDHHC9) involved in the post‐translational modification and intracellular trafficking of specific target substrates." (PMID 40308169, 2025). "In humans, X-chromosome-linked intellectual disability has been linked to over 100 gene mutations, including ZDHHC9 and ZDHHC15 genes." (PMID 36766729, 2023). "Mutations in the gene encoding zDHHC9 cause mild-to-moderate intellectual disability, seizures, speech and language impairment, hypoplasia of the corpus callosum and reduced volume of sub-cortical structures." (PMID 29944857, 2018). "The current study investigated structural brain differences of individuals with mutations in ZDHHC9, which is associated with a specific neurodevelopmental phenotype including prominent speech and language impairments and intellectual disability." (PMID 27747153, 2016). "Overall, this study highlights a key role for zDHHC9 in brain development and behaviour, and supports the utility of the Zdhhc9 mutant mouse line to investigate molecular and cellular changes linked to intellectual disability and other deficits in the human population." (PMID 29944857, 2018). "Finally, the ZDHHC9 mutant mouse line could provide a model system to better understand the mechanism of pathological neurodevelopmental changes that lead to intellectual disabilities associated with X-chromosome mutations." (PMID 36766729, 2023). "The current study redressed this by investigating brain network dynamics in a neurodevelopmental disorder of known genetic origin, by comparing individuals with a ZDHHC9‐associated intellectual disability to individuals with no known impairment." (PMID 31639257, 2020).
pancreatic cancer (8 papers, 2023 to 2025). "ZDHHC9 is associated with inhibition of the pancreatic tumor microenvironment along with the K-Ras gene." (PMID 40681504, 2025). "In ZDHHC9-deficient mouse models, pancreatic tumors exhibit a higher proportion of activated effector T cells, shifting the tumor microenvironment from a suppressive to a pro-inflammatory state." (PMID 40681504, 2025). "Likewise, in pancreatic cancer models, ZDHHC9 overexpression was linked to impaired anti-tumor immunity, whereas knocking down ZDHHC9 converted the TME from immunosuppressive to immune-active and improved treatment responses." (PMID 40740766, 2025). "Research indicates that ZDHHC9 is overexpressed in pancreatic cancer tissues and correlates with diminished antitumor immunity." (PMID 40066091, 2025). "In pancreatic cancer, for example, genetic silencing of ZDHHC9 was shown to sensitize tumors to anti-PD-L1 immunotherapy, effectively overcoming resistance to checkpoint blockade." (PMID 40740766, 2025). "Our conclusion is supported by parallel evidence in other cancers: In a recent pancreatic cancer study, ZDHHC9 silencing transformed the tumor milieu from “cold” to “hot” and dramatically sensitized tumors to anti-PD-L1 therapy in vivo." (PMID 40740766, 2025). "In pancreatic cancer, ZDHHC9 overexpression correlates with impaired immunity." (PMID 40977744, 2025). "ZDHHC9 overexpression in pancreatic cancer correlates with poor prognosis." (PMID 40977744, 2025). "Notably, ZDHHC9-mediated LDHA palmitoylation is upregulated in gemcitabine-resistant pancreatic cancer." (PMID 40977744, 2025). "zDHHC9 silencing with nanoparticles also induced a considerable regression of pancreatic tumors and extended the survival of mice with transplantable pancreatic tumors, enhancing inflammation and infiltration of anti‐tumor immune effector cells and boosting anti‐PD‐L1 immunotherapy." (PMID 39429488, 2024). "More recently, roles of ZDHHC9 in anti-tumor immunity were also revealed in pancreatic cancer." (PMID 37759431, 2023). "The overexpression of ZDHHC9 in pancreatic tumors inhibits host antitumor immunity, suggesting that downregulating ZDHHC9 may be a practical immunotherapeutic approach with anti-PD-L1 therapy for pancreatic cancer." (PMID 40066091, 2025). "In pancreatic cancer, knockdown of ZDHHC3 impaired tumor progression in a xenograft mice model, whereas inactivation of ZDHHC9 modified the tumor microenvironment from an immunosuppressive to a proinflammatory environment and, thus, suppressed tumor growth." (PMID 37759431, 2023).
X-linked intellectual disability (8 papers, 2015 to 2025). An X-linked intellectual deficiency in which not enough information is known, reported or published to indicate whether a gene causes non-syndromic or syndromic presentations. "ZDHHC9 palmitoylates myelin basic protein (MBP) in cultured cells and in vivo, and certain ZDHHC9 X-linked intellectual disability (XLID) mutants display residual protein acyltransferase (PAT) activity towards MBP." (PMID 41031565, 2025). "HA-ZDHHC9WT localizes to puncta in oligodendrocyte (OL) processes, but other protein acyltransferases (PATs), and X-linked intellectual disability (XLID) mutant forms of ZDHHC9, are restricted to OL cell bodies." (PMID 41031565, 2025). "Mutations in the ZDHHC9 gene, which is located on the X chromosome, have been identified in ~2% of individuals with X-linked intellectual disability (ID)." (PMID 35819139, 2022). "All known cases of X-linked intellectual disability (XLID) due to ZDHHC9 mutation in the United Kingdom were invited to participate in a study of neurocognitive and neuroimaging phenotypes." (PMID 26000327, 2015). "Additionally, the ZDHHC9 mutations linked to X-linked intellectual disability result in reduced protein stability and DHHC9-GCP16 complex formation." (PMID 37035671, 2023). "Furthermore, loss of function mutations in ZDHHC9 result in X-linked intellectual disability (XLID), with affected individuals displaying neurodevelopmental delay, seizures, and facial dysmorphism." (PMID 37035671, 2023). "We chose to further study ZDHHC2 and ZDHHC5 as they have been shown to regulate activity-induced palmitoylation of synaptic proteins, as well as ZDHHC8 and ZDHHC9 as their function is disrupted in a subset of patients with schizophrenia and X-linked intellectual disability, respectively." (PMID 37039765, 2023). "X-linked intellectual disability (XLID) is often ascribed to neuronal deficits, but here we report that expression of human and mouse ZDHHC9 orthologs is far higher in myelinating oligodendrocytes (OLs) than in other CNS cell types." (PMID 41031565, 2025).
colorectal cancer (6 papers, 2007 to 2025). A primary or metastatic malignant neoplasm that affects the colon or rectum. "Indeed, analyses in other cancers reinforce this concept: in colorectal cancer, high ZDHHC9 was associated with worse survival and was shown to promote tumor growth by upregulating PD-L1 and blunting CD8+ T cell immunity." (PMID 40740766, 2025). "Although DHHC3 mediates PD-L1 S-palmitoylation in colorectal cancer (CRC) cells, ZDHHC9 is identified as the primary S-palmitoylation enzyme for PD-L1 in other cancers, lung adenocarcinoma, PDAC and BrCa, ZDHHC9-mediated S-palmitoylation stabilizes PD-L1, promoting immune evasion." (PMID 40335986, 2025).
epilepsy (6 papers, 2015 to 2025). A brain disorder characterized by episodes of abnormally increased neuronal discharge resulting in transient episodes of sensory or motor neurological dysfunction, or psychic dysfunction. "The cognitive deficits and epilepsy that are hallmarks of ZDHHC9-associated XLID are often ascribed to malformations of neocortical gray matter." (PMID 41031565, 2025). "Mutations in the X-linked ZDHHC9 gene cause cognitive deficits in humans, with a subset of patients suffering from epilepsy." (PMID 41031565, 2025). "Rolandic epilepsy is another relevant neurodevelopmental condition for comparison due to the overlapping phenotype of expressive language deficits and epilepsy with centro-temporal spikes that were also observed in the carriers of ZDHHC9 mutation." (PMID 28168288, 2017). "Seven out of nine males with ZDHHC9 mutations had been diagnosed with epilepsy, exceeding epilepsy risk in XLID comparison subjects (P = 0.01)." (PMID 26000327, 2015). "For individuals diagnosed with ZDHHC9 mutations, results of this study have prognostic significance since epilepsy can be anticipated and support can be targeted to promote expressive communication skills." (PMID 26000327, 2015). "The identification of a single ZDHHC9 mutation case with focal seizures during adulthood could reflect different pathophysiology of epilepsy in the ZDHHC9 group versus idiopathic RE, or underreporting of late seizures in individuals susceptible to RE, or an unrelated pathology in this case." (PMID 26000327, 2015).